CD4 (CD4 molecule)
Diseases named in the same sentence as CD4 in open-access papers (continued):
Sharing a sentence is not in itself a finding about the gene and the disease.
co-infection (continued). "Although CD4+ T cell epitopes have been fine-mapped and the tools for peptide-loaded HLA class II tetramers are available, investigations of single-epitope specific CD4+ T cells in HBV/HDV co-infection are still lacking." (PMID 35215790, 2022). "Notably, individuals with latent TB infection co-infected with helminths had lower frequency of CD4+IFN-γ+ T cells and increased in CD4+FoxP3+ T cells (Tregs) compared to those without helminth co-infection." (PMID 34220854, 2021). "Notably, there are previous reports of elevated levels of soluble inflammatory and cellular activation (monocyte and CD4+ and CD8+ T cells) markers in older chronic HCV-infected individuals with/without HIV co-infection." (PMID 35062255, 2021). "Furthermore, patients co-infected with HIV and GB virus C have higher baseline CD4+ T cell counts, a slower rate of decline of CD4+ T cells, and lower plasma levels of HIV RNA than HIV-positive patients without GB virus C co-infection." (PMID 33672615, 2021). "Important clinical and laboratory markers such CD4+ count, duration of HIV infection and presence of co-infection which could influence the HRQoL were not captured in this study." (PMID 34603582, 2021). "The main objective of this secondary data analysis was to assess whether the pre-HAART CD4+ T-lymphocyte counts and percentages can be used as biomarkers of post-HAART immune recovery in HIV-infected children with and without TB co-infection." (PMID 33059622, 2020). "The main objective of our study was to assess whether the pre-HAART CD4+ T-lymphocyte counts and percentages could serve as biomarkers for post-HAART treatment immune-recovery in HIV-positive children with and without TB co-infection." (PMID 33059622, 2020). "In order to determine whether HIV infection specifically influenced M. tuberculosis-specific CD4 T-cell responses in the present study, HAd5-specific CD4 T-cell responses were also assessed in LTBI with or without HIV coinfection." (PMID 30541853, 2019). "Furthermore, in a macaque model of TB/SIV co-infection, suppression of LTBI reactivation was shown to be independent of CD4+ T cells in at least one third of animals." (PMID 30949177, 2019). "To determine whether HIV infection might specifically impact M. tuberculosis-specific CD4 T-cell responses, we also assessed HAd5-specific T-cell responses in LTBI with or without HIV coinfection in the same volunteers." (PMID 30541853, 2019). "Patients with MDR-TB/HIV coinfection should be provided with early diagnosis, timely access to second-line anti-TB drugs, motivational counseling, and early ART, as soon as MDR-TB treatment is tolerated, regardless of CD4 count." (PMID 30596734, 2018). "In the present cohort of PLWHIV all individuals were on long-term stable treatment with cART, had a normalized CD4+ T cell count (mean 592, SD± 256 cells/uL), had suppressed viral replication, no IDU, no co-infection with HCV or HBV or other apparent comorbidities." (PMID 29491459, 2018). "However, we had contrary observation to a study in Cameroon reporting that the mean CD4 count in HIV and malaria co-infection was not significantly different from that of HIV mono infection (F 0.004,p = 1.000)." (PMID 28346490, 2017). "Thus, hierarchy low CD4+ T cell counts and Th1 cells in HIV-1-infected humans correlate with increased occurrence of active TB, but not M. tb co-infection." (PMID 26959228, 2016). "In this context, the current study was designed to evaluate the outcome of Malaria-CL infections, the CD4 and CD8 T-cell profiles as well as the Th1/Th2 cytokine levels in a co-infection murine model (BALB/c) of P. yoelii 17XNL (non-lethal) and L. amazonensis or L. braziliensis." (PMID 27446022, 2016). "CD4+ MTB-specific T-cells secreting both IFN-γ and IL-2 were reduced in frequency in individuals with HIV-TB co-infection (whether active or latent) unlike other IL-2 secreting subsets." (PMID 26756579, 2016).
co-infection (continued). "In order to potentially harness non-CD4 immune cell subsets in settings where adaptive immune responses are absent or impaired, such as Mtb/HIV co-infection, it would be desirable to not only boost their numbers and differentiation capacity but also to induce IFN-γ secretion." (PMID 27391012, 2016). "However the proportion of the total response to PPD or MTB peptides contributed by CD4+ T-cells secreting IFN-γ and IL-2 together was lowest in active TB/HIV compared with LTBI without HIV co-infection." (PMID 26756579, 2016). "MTB-specific CD4+ functional effector cells secreting IFN-γ alone, TNF-α alone or IFN-γ and TNF-α more frequently expressed CD127 compared with EBV and/or CMV-specific cells in those without evidence of HIV co-infection." (PMID 26417433, 2015). "In those without HIV co-infection PPD-specific CD4+ cells secreting IFN-γ with or without TNF-α and expressing CD127 were relatively more frequent but this expression was reduced in HIV co-infection indicating that these cells might be relatively short-lived." (PMID 26417433, 2015). "In children, CMVpp65-specific CD4+ T cells had a mature CD27low effector memory phenotype and a high capacity for Mip-1β production similar to those detected in adults, and there was no apparent effect of HIV co-infection." (PMID 25974183, 2015). "Second, even if the WHO HIV clinical staging is considered an acceptable disease severity marker, the lack of information on CD4 and CD8 T cell counts is still an important limitation, in relation to the influence of HIV co-infection on the cytokine response during falciparum malaria." (PMID 25503583, 2014). "The results of our subgroup analyses in cohorts largely exposed to HAART provide additional support to WHO's revised guidelines which include promoting the initiation of ART for all those with HIV/TB co-infection, irrespective of WHO disease stage or CD4 cell count." (PMID 21209936, 2010). "Interestingly, one study observed that immune recovery is associated with a persistent increase in plasma HCV RNA, especially for those with baseline CD4+ T-cell counts <350 cells/mm, and HCV co-infection did not antagonize the CD4+ T-cell response to HAART." (PMID 19098990, 2008). "We further observed significantly lower secretion of IFN-γ in CD8+ T cells but no significant change of IFN-γ secretion in CD4+ T cells in the HT group in comparison to the TB group, suggesting that HIV/TB co-infection might mainly affect the secretion of IFN-γ in CD8+ T cells." (PMID 37483385, 2023). "Another study demonstrated that DENV/ZIKV co-infection decreased the ability of CD4+ T cells to produce IFN-γ+ and TNF+ compared to single DENV and ZIKV infections, showing the lack of cross-reactivity between DENV and ZIKV specifically CD4+ cells for envelope and NS1 proteins." (PMID 35215836, 2022). "Reduced CD4+ examinations would provide a significant cost saving: if all stable patients were monitored once per year, the total expenditure would be reduced by 63%, whereas it would be decreased by 50% by monitoring stable patients without HCV annually and those with HCV co-infection twice a year." (PMID 28166729, 2017). "However, we recently found that co-infection with acute lymphocytic choriomeningitis virus (LCMV) in C57BL/6 mice leads to exacerbated skin immunopathology in L. braziliensis-infected mice, which depends on CD8+ T cells, and not NK cells or CD4 T cells." (PMID 28192528, 2017). "However, no detectable differences in the timing of the onset of HIV gene expression upon co-infection of YFP-HIV with unlabeled virus and no detectable differences when primary CD4+ cells were co-infected with two viruses argues against the presence of cooperativity at the onset of gene expression." (PMID 27812216, 2016).
co-infection (continued). "The study showed that treatment of ascariasis had a significant effect on CD4+ T-cell count increase in the treated Pre-ART Ascaris lumbricoides/HIV co-infected individuals; whereas the same positive effect was not evident for other intestinal helminth/HIV co-infection detected in this study." (PMID 26415705, 2015). "Co-infection with HBV and/or HCV did not significantly affect viral load or CD4 count, but we identified a borderline increase (p = 0.05) in the diversity of HIV sequences (not shown;), suggesting that diversification of HIV may be faster in the presence of HBV and/or HCV." (PMID 23469241, 2013). "Ag ELISA sensitivity remained low regardless of CD4 count, suggesting that factors beyond systemic immune cell counts, such as localized immune responses or the specific nature of antigen secretion by cysts, might be more critical for this assay in HIV co-infection." (PMID 41003557, 2025).
influenza (814 papers, 2005 to 2026). An acute viral infection of the respiratory tract, occurring in isolated cases, in epidemics, or in pandemics; it is caused by serologically different strains of viruses (influenzaviruses) designated A, B, and C, has a 3-day incubation period, and usually lasts for 3 to 10 days. "Influenza vaccination has been linked to CD11b+ DC expansion, enhancing CD4+ T cell priming and antibody responses." (PMID 40951841, 2025). "A rapid decline in CD4 T lymphocytes, especially with concurrent influenza, increases the risk of Pneumocystis jirovecii pneumonia (PCP)." (PMID 40260188, 2025). "Preexisting influenza antibodies and higher CD4+ cell counts were associated with better vaccine responses to each of the three vaccine components measured by the hemagglutinin inhibition assay." (PMID 38792562, 2024). "We need vaccines to generate strong multifunctional CD4 memory against potentially deadly pathogens such as influenza and SARS-CoV2 that rapidly mutate and evade Ab-mediated protection." (PMID 38152398, 2023). "In the case of mild infections caused by seasonal IVs, the CD8+ and/or CD4+ T cells provide considerable defense against influenza infection if these cells are already present in the host in sufficient numbers." (PMID 36992177, 2023). "We demonstrated homosubtypic and cross-strain protection against influenza infections was associated with T cell response, especially CD4 T cell response." (PMID 35858844, 2022). "In children immunized with a quadrivalent influenza vaccine, CD4+ Tfh accumulated in tonsils and were associated with the frequency of influenza strain specific antibody secreting cells." (PMID 36275655, 2022). "A human challenge study demonstrated that pre-existing CD4+ T-cells responding to internal influenza proteins were associated with lower virus shedding and less severe illness." (PMID 36052083, 2022). "In summary, we identified the genes/proteins and pathways essential for cell activation and function in CD4+ T cells that are associated with differences in influenza vaccine-induced humoral immunity by vaccine type." (PMID 36560767, 2022). "Several CD4 T cell subsets have been implicated in the lung response to influenza infection, namely T helper 1 (Th1), T helper 2 (Th2), and regulatory T cell (Treg) subsets." (PMID 34962049, 2022). "Intranasal administration of attenuated influenza viral vaccine increased the levels of CD4+ TRM cells in lungs of mice that resulted in long-term protection against influenza variants." (PMID 36211412, 2022). "Though antibodies have been the hallmark of protection against influenza vaccines and infection, CD4+ T cells confer protection too44,45." (PMID 34262052, 2021). "Robust T cell control of heterosubtypic influenza infection has been closely associated with the development of mucosally residing tissue resident memory (TRM) CD4+ and CD8+ cells." (PMID 33767689, 2020). "In our cohort, there was a trend towards an association between the presence of polyfunctional CD4 + T-cells at influenza diagnosis and reduced disease severity." (PMID 32572168, 2020). "Further, we observed that PLP-based adjuvants afforded strong and durable protection from influenza challenge that was closely associated with distinct functional recall profiles of CD4 and CD8 T cells unique to the PLP vaccine formulation." (PMID 33767689, 2020). "As with CD8+ T cells, adoptive transfer of CD4+ memory T cells in mice was associated with greater protection during influenza infection." (PMID 32117155, 2020). "No impact of age, gender, underlying diseases, immunosuppressive agents and steroids use, CD4+ T cell count on incidence of influenza associated aspergillosis was observed." (PMID 33537328, 2020). "Severe influenza was also associated with downregulation in immune response pathways, including pathways involved in antigen presentation such as CD4+ T-cell co-stimulation, CD8+ T cell and Natural Killer (NK) cells effector functions." (PMID 32066441, 2020).
influenza (continued). "In studies of influenza challenge, CD4+ memory T cells in blood were associated with a reduction in symptoms on subsequent infection." (PMID 31815739, 2020). "Influenza is a self-limited upper respiratory tract infection that causes acute and severe systemic symptoms and its spread to the lungs is limited by CD4+ T-cell responses." (PMID 33062077, 2020). "But reduction of CD4+ T cells was proved to be associated with higher mortality of severe influenza patients with aspergillosis, especially in patients with CD4+ T cells count < 200 cell/μL." (PMID 33537328, 2020). "Description of prominent CD4+ T cell responses being strong in numbers, by contrast, are primarily associated with severe influenza cases." (PMID 31539406, 2019). "We report that the influenza vaccine responsiveness of an aged population was associated with age-related homeostatic dysregulation involving T-cell proliferation in CD4 and CD8 T-cell maturational subsets." (PMID 31312227, 2019). "Previous research demonstrated that aging-induced changes in the subpopulations of effector T cells and regulatory CD4+ T lymphocytes is associated with poor responses to influenza vaccination." (PMID 31707363, 2019). "They found that RAE-1 expression by DCs did not affect effector T cell responses, but conferred a high rate of survival of CD4+ T cell-deficient animals in a model of influenza in which viral elimination is ordinarily CD4+ T cell-dependent." (PMID 29483917, 2018). "Pre-existing influenza-specific CD4+ T cells were associated with decreased illness severity following influenza challenge of healthy volunteers lacking neutralizing antibodies." (PMID 29866115, 2018). "Patients carrying this mutation displayed impaired immune responses following TIV influenza vaccination, which are characterized by decreased CD4+ T-cell expansion and antibody avidity." (PMID 29649134, 2018). "We utilized surface expression of CD38 on newly activated CD4 memory T cells as a strategy to identify type 1 diabetes associated autoreactive T cells activated by influenza vaccination in healthy subjects." (PMID 30619245, 2018). "Pre-existing CD4+ T cells were also associated with disease protection and lower virus shedding during influenza infection." (PMID 29467737, 2018). "T cell epitopes demonstrated extensive cross-reactivity between diverse influenza strains in outbred animals, with NP implicated as a significant antigenic target demonstrating extensive cross-reactivity for both CD4+ and CD8+ T cells." (PMID 29666412, 2018). "Studies have shown that cellular responses play an important role in protection, with associations drawn between pre-existing IFN-γ -producing influenza-specific CD4+ and CD8+ T-cells and less severe disease." (PMID 30573748, 2018). "Loss of Blimp-1 in CD4 T cells leads to reduced ThCTL in the lungs, and, in others studies, reduced ability to prevent weight loss after influenza." (PMID 29632538, 2018). "The precise mechanisms by which CD4 T cells can provide protection against lethal or highly pathogenic influenza infection were identified in a transgenic mouse model of PR8 infection." (PMID 28167943, 2017). "Granzyme B has been associated with clinical protection from influenza and is produced by both CD4+ and CD8+ T-cells." (PMID 28769922, 2017). "In any case, these findings provide evidence that both TFH1 ICOS+ and antigen-specific CD4+IL-21+ICOS+CXCR5+ TFH cell subsets are associated with functional antibody responses to influenza vaccination." (PMID 27336786, 2016). "HIV as well as a number of acute viral infections such as Influenza, cytomegalovirus and Epstein-Barr virus are typically associated with an inversion of the CD4:CD8 ratio." (PMID 27129582, 2016). "Influenza-induced gastroenteritis was caused by lung-derived CD4+ T cell-induced dysbiosis that resulted in the expansion of Th17 cells and subsequent intestinal injury." (PMID 27148490, 2016).